FOXP3 (forkhead box P3)
Diseases named in the same sentence as FOXP3 in open-access papers (continued):
Sharing a sentence is not in itself a finding about the gene and the disease.
tumor (continued). "To compare the composition of CD8+ and Treg cells in the tumor tissues, tumor-free tissues and tumor margin tissues of GC patients, we analyzed the proportions of CD8+ T cells and Foxp3+ Tregs using IHC." (PMID 33093811, 2020). "Irrespective of age group, several immune subtypes were unequally distributed across the tumor zones: CD20+ cells predominantly resided in the invasive front, and FOXP3+ cells represented a higher proportion of immune cells in the tumor centre." (PMID 33024560, 2020). "Significant differences in the density of FOXP3-positive TILs, CD204-positive tumor-infiltrating macrophages, PD-L1-positive cells, and colony-stimulating factors were observed." (PMID 33121123, 2020). "An analysis of an inflammatory infiltrate of tumor stroma showed a correlation of CD68, iNOS and FOXP3 with a histological type of tumor." (PMID 32933105, 2020). "MDSCs are recruited from peripheral lymphoid organs to tumour sites, promoting the production of CD4+Foxp3+Tregs." (PMID 33308251, 2020). "Among the tumor-infiltrating CD4 T cells, essentially all of the Foxp3+ population expressed high levels of cell surface CTLA-4." (PMID 31991588, 2020). "It acts on both tumor cells, inhibiting Akt and ERK1/2 signaling pathways, and immune populations, increasing intratumoral CD8 + T cells and reducing FOXP3 + Treg cells." (PMID 32892748, 2020). "Compared with pre-infusion tumor tissues, post-CAR-T cell infusion tumor specimens show markedly upregulated expression of many immunosuppressive molecules, particularly IDO1 and Foxp3, and in some cases, IL-10, PD-L1, and/or TGF-β." (PMID 32117960, 2020). "Accumulation of FoxP3+ Treg in the TME of various malignancies, favoring tumor progression is widely reported." (PMID 32041340, 2020). "Staining of tumor sections with antibodies against CD3, CD4, CD8 and Foxp3 confirmed that the lymphocytes isolated on in vitro digestion were of intratumoral origin rather than peripherally associated with the excised tumors." (PMID 32461349, 2020). "However, tumor cells often induce an immunosuppressive microenvironment that favors the development of immunosuppressive populations of immune cells, such as myeloid-derived suppressor cells (MDSCs), M2 macrophages, regulatory Foxp3+ T cells (Tregs), and PD-1+ T cells, to escape immune responses." (PMID 32153559, 2020). "The strong negative correlation of MCP‐1 with global sTILs % was further substantiated by its inverse relationship with whole tumor density of CD3+, CD5+, CD8+ and FOXP3+ cells." (PMID 33024560, 2020). "But, a significant inverse correlation between miR‐23a and CCL22 or Foxp3 was found from HBV‐ tumor group and HBV+ tumor group." (PMID 31769216, 2020). "The IL12A AA haplotype included rs583911 and rs568408 and was an independent predictor of worse survival, together with the follicular patterns of T-cells (FOXP3+ and CD8+) and high IL-17F tumor levels." (PMID 32913559, 2020). "Foxp3+ Tregs accumulated in the tumor, but most CD8+ T cells sequestered at the tumor margin and in tumor-free tissues." (PMID 33093811, 2020). "We detected tumor infiltrating CD4+, CD8+ and FOXP3+ T cell proportion in TILs of ILT4-high or ILT4-low patients respectively." (PMID 32368343, 2020). "Tumoural parenchyma was immunohistochemically counted manually for the number of CD8, CD4 and Foxp3 cells." (PMID 32758195, 2020). "As the infiltration of TIL subsets was correlated with one another, we also analyzed the relationship between the ratios of TIL (FOXP3+/CD8+ TIL, FOXP3+/CD4+ TIL, and CD4+/CD8+ TIL) and tumor recurrence." (PMID 32216826, 2020). "Another transcription factor, Foxp3, promotes tumor growth by suppressing IL-10- and/or TGF-β-mediated tumor cell killing after increased infiltration of Treg cells." (PMID 32775468, 2020).
tumor (continued). "Our findings showed that all these Treg markers were increased in infiltrating Vδ1+ T cells from either tumour or normal BC tissue, and only CD73 and FoxP3 expression was increased in infiltrating Vδ2+ T cells." (PMID 32345959, 2020). "Differences were analyzed in the expression of vascular endothelial growth factor receptor‐2 (VEGFR2) and the number of Foxp3+ Tregs and hypoxia‐inducible factor (HIF)‐1α+ cells in tumor tissues sampled at the first and second (recurrence) surgeries." (PMID 32267594, 2020). "PD-L1 tumor cell expression was positively correlated with CD8+/GrB+ CTLs, FOXP3+ Tregs, PD-1+ T cells, and CD68+ TAMs." (PMID 32635549, 2020). "In summary, our data demonstrate that VDR and FOXP3 are expressed in CHL and that there is a direct correlation between VDR expression and quantity of FOXP3 expressing lymphocytes in CHL tumor microenvironment." (PMID 32513132, 2020). "CD4+Foxp3+Helios+ Treg cells co-expressed the suppressive molecules PD-1, CTLA-4, and CD39, suggesting that the phenotype of these Treg cells in the tumor of CRC patients is highly suppressive." (PMID 32674255, 2020). "Taken together, Tregs, especially FOXP3(hi) Tregs, promote comprehensive immunosuppression in the TME to assist tumor initiation and progression of CRC." (PMID 33419310, 2020). "Tumor infiltration of IBA-1 positive cells was significantly decreased after Rab27a knockdown, while infiltration of FoxP3 positive regulatory T cells showed an upward trend." (PMID 33282910, 2020). "CTLA-4 is also constitutively expressed by the FoxP3+CD4+CD25+ tumor infiltrating regulatory T cells (Tregs), which are important negative regulators of tumor immunity and of autoimmunity." (PMID 32443877, 2020). "CD4+ lymphocytes were the most prevalent subtype in tumour stroma and at tumour edge and CD8+ lymphocytes were most prevalent in tumour nests; FoxP3+ lymphocytes were rarest in all compartments." (PMID 32577938, 2020). "The transcription factor forkhead box P3 (FOXP3) is specifically expressed by Tregs, which is involved in the differentiation and development of Tregs and tumor immune escape." (PMID 33344447, 2020). "Studies were included, in which the prognostic significance of intratumoral tumor infiltrating lymphocytes, as well as subsets of CD3, CD8, FOXP3, CD45R0 lymphocytes, were determined within the solid tumor center, the invasive margin, and tumor stroma." (PMID 32099066, 2020). "In the post-vaccination tumor, the expression of cleaved caspase 3 was co-localized in endothelial cells with CD34-positive staining and Foxp3-positive cells." (PMID 32164575, 2020). "There was no direct association of CA9 with PD-L1 expression or the density of TILs in the tumour stroma, but CA9 was directly related to the extent of FOXP3+ TIL density (p = 0.008)." (PMID 32066909, 2020). "High expression of CD4_C12-CTLA4 (tumor regulatory T cell, Tumor-Treg) markers, such as CCR8, RTKN2, and FOXP3, was observed in C1." (PMID 33584715, 2020). "IP1 identifies 5 different cell types in the tumor microenvironment: CD3+ T cells, CD20+ B cells, CD3+FOXP3+ regulatory T cells (Treg), CD117+CK- mast cells, and CK+ epithelial/tumor cells." (PMID 33590360, 2020). "The numbers of infiltrating FoxP3+ T-cells and CTLA-4+ cells in tumor stroma were greater than those in tumor parenchyma." (PMID 32785290, 2020). "Presence of tumor in all three models lead to a reduction in CD4+ T cells, with a greater proportion of these cells being FoxP3+ Treg cells within the spleens of mice bearing NXS2 tumors." (PMID 33028899, 2020). "Webb and coworkers have demonstrated that PD-L1+ cells often occur collectively with CD8+, CD4+, and PD-1+ tumor-infiltrating T cells, CD25+FoxP3+ Tregs, and other TIL populations." (PMID 33062717, 2020). "According to previous literature, the immune microenvironment in tumor tissues is closely related to the balance of CD8+ T cells and FoxP3+ Treg cells." (PMID 32366856, 2020).
tumor (continued). "FOXP1 and FOXP2 fall under the FOXP sub-family (also comprising FOXP3 and FOXP4) which has functions in oncogenic and tumor suppressive pathways." (PMID 32066696, 2020). "It is significantly higher in tumor tissues than in ANT and PBMC, expressing FOXP3, CD25, ICOS, and so on." (PMID 32659053, 2020). "Our data indicated that TOC significantly increased the TTP for dogs with adenocarcinomas, and decreased the number of intratumoral Foxp3+ Tregs and HIF‐1α+ tumor cells, as well as inhibited VEGFR2 expression." (PMID 32267594, 2020). "The mRNA expression data prompted us to stain tumour sections to validate immune-related expression, by which we chose seven immunophenotypical markers [CD45, CD4, CD8, FOXP3, CD79A, Kappa/Lambda (K/L) and SLAMF7] to study both T cell and B cell expression." (PMID 32195184, 2020). "As such, assessing lymphocyte densities as ratios such as CD8/FOXP3 or CD4/CD8 has been investigated and has shown to have prognostic potential in certain tumor types, but warrants further validation and systematic investigation." (PMID 33013886, 2020). "Mechanistically, cancer-FOXP3 directly transactivates CCL5, and the CCL5-CCR5 axis promotes Treg cell accumulation in tumor lesions from peripheral blood in vitro and in vivo." (PMID 32425930, 2020). "Mice treated with pembrolizumab showed an escalation of exhausted T cells expressing TIM-3, and LAG-3 in tissues, higher levels of several human cytokines in plasma and high densities of FoxP3+ regulatory CD4+ and CD8+ T cells in the tumor microenvironment." (PMID 33511078, 2020). "Interestingly, chronic immunotherapy with cytokine-loaded microspheres could not control tumor burden due to a progressive decline in the intensity of antitumor T cells and an increase in tumor-infiltrating CD4+CD25+Foxp3+ T suppressor cells with repeated injections." (PMID 33178203, 2020). "IME profiles, including PD‐L1 tumor proportion score (TPS), stromal CD8 tumor‐infiltrating lymphocyte (TIL) density, and stromal Foxp3 TIL density, were quantified by digital pathology using a machine learning algorithm." (PMID 32400056, 2020). "The CD4+ regulatory T cells (Tregs) are characterized by the expression of Forkhead Box P3(FOXP3) and CD25+ and are commonly described as tumor-promoting TILs." (PMID 32235370, 2020). "No striking differences were observed in the proportion of helper T-cells (CD4+), Foxp3+ T-cells and cytotoxic T-cells (CD8+) among the different treatment groups in the tumor." (PMID 32231867, 2020). "For example, CD4 T‐cells responding to tumors with oncogenic RAS often differentiate into forkhead box P3 (FOXP3)‐expressing regulatory T‐cells (Tregs), likely due to increases in IL‐10 and TGF‐β expression by tumor cells." (PMID 33073260, 2020). "A positive link between cancer-FOXP3 expression levels and Treg cell accumulation in pancreatic ductal adenocarcinoma (PDAC)-derived tumor tissues was recently shown." (PMID 32425930, 2020). "Data on the total tumor density, density in the tumor stroma and density in tumor epithelial areas of cells positive for CD4, FoxP3 and CD45RO were therefore collected from the CD8a-high cases of the U-CAN study population." (PMID 33153037, 2020). "Although their approach differed from ours (general immune status versus microenvironment of tumor), there are several features common to both approaches, such as increasing CD4+FOXP3+ and increased TGFβ-Treg cells with ROS competition." (PMID 32977478, 2020). "The main mechanism of tumor immune evasion is immunosuppression in the tumor microenvironment mediated by CD4+, CD25+, and FoxP3+ cells, regulatory T cells (Tregs) and other types of inhibitory cells." (PMID 32226026, 2020). "Murine models of cancer have shown that depleting Treg (using specific ablation of Foxp3 or anti-CD25 antibodies) lead to enhanced anti-tumor immune responses, demonstrating the biological significance of these cells to tumor progression." (PMID 33013886, 2020).
tumor (continued). "IP1 includes markers for T cells (CD3), Treg cells (FOXP3), B cells (CD20), mast cells (CD117), tumor/epithelial cells (CK), and a proliferation marker (Ki67)." (PMID 33590360, 2020). "In a tumor, CD11b+CX3C1+ macrophage subset has been shown to induce CD4+ Foxp3+ cells, and its depletion leads to reduced tumor growth." (PMID 33371444, 2020). "This is hinted by the comparison of nodes with discordant treatment effects, which demonstrated an increased number of tumor-infiltrating CD8 T cells and CD163+ macrophages and decreased stromal FoxP3+ Tregs in nodes with 100% TE." (PMID 33344227, 2020). "For instance, when CD4+FOXP3+ T cells were used as the RC, the MIN distance of tumor cells was 11.12 μm of P2433 and 28.83 μm of P7422; the MIN distance, of CD8+ T cells, was 19.60 μm of P2433 and 8.6 μm of P7422." (PMID 32377339, 2020). "FOXP3 arrests HCC growth by suppressing the proliferation, migration and invasion of the tumor cells and promotes apoptosis in HCC cells." (PMID 33116119, 2020). "As an indicator of the balance between CD8+ TILs and Foxp3 Tregs in the tumour microenvironment, the CD8/Foxp3 ratio appeared to be useful for predicting clinical outcomes." (PMID 32758195, 2020). "We found that stathmin was significantly associated with VEGF and vascular proliferation as well as with the immune response markers FOXP3, CTLA4, PD-L1 and PD-1 in tumour tissues." (PMID 32076022, 2020). "Here, we selected tumor immunity-related biological markers, including CD8, FOXP3, and CD163, which, respectively, represented CD8+ T cells, FOXP3+ Treg cells, and CD163+ M2 macrophages to analyze different advanced GC types." (PMID 32983971, 2020). "Together with STAT5, STAT3 stabilizes Foxp3 expression in response to IL-2; IL-23-driven STAT3 activation in tumor-infiltrating Treg cells achieves the same phenotype." (PMID 33143070, 2020). "Eos had an additional, Foxp3 mRNA-independent, positive correlation with Foxp3 protein level in NSCLC tumor Treg cells." (PMID 32425930, 2020). "The third cluster (fC3, 56%) was dominated by the increased anti-tumor immune responses of CD3+; CD45ro+; and FoxP3+ TILs, CD68+ TAMs, as well as tumors of deep location." (PMID 32560244, 2020). "Analyses of 7 GCT specimens showed that 4.0% of total tumor single cells suspensions were CD8+ T cells, 3.3% were CD4+ T cells and 0.72% were CD4+CD25+FOXP3+ Tregs." (PMID 32814714, 2020). "AA tumor samples present significant fold-change elevation in gene expression compared with CA for Interleukin 8 (IL8), forkhead box P3 (FOXP3), and Interleukin 1 beta (IL1B) genes." (PMID 33425763, 2020). "To evaluate the impact of tumor-endothelial PD-L1 on the infiltration of CD8+ T cells and FoxP3+ T cells, we selected two xenograft animal models (MC38 and B16 cell lines)." (PMID 32366856, 2020). "To evaluate the number of Foxp3+ Tregs in NPC, we studied 177 tumor tissues from individuals with untreated patients." (PMID 32573058, 2020). "To assess the mechanism of NARA1leukin’s anti-tumor effects, we analyzed the composition of tumor-infiltrating lymphocytes (TILs) with a particular interest in the ratio of CD8+ T to CD4+ Foxp3+ Treg cells." (PMID 33353953, 2020). "Local immune responses in patients with HCC are restrained by tumor and circulating CD4+/CD25+/FoxP3+ Tregs, which suppress effector CD4+ T-cell activity and proliferation." (PMID 31903159, 2020). "By immunohistochemical analysis, in tumor tissue, the median level of CD3+ cells/HPF was 40 (range, 16–126), CD8+ cells/HPF was 22 (range 5-65), and FOXP3+ cells/HPF was 5 (range 0-46)." (PMID 32884895, 2020). "Although the technology used to detect tumor immunological information by EXs likely needs to be more specific, tumor tissue examination has elucidated the involvement of PD1, PDL1, CD8 and FOXP3." (PMID 32659892, 2020).
tumor (continued). "We further examined the proportions of CD4+ T cells, CD8+ T cells, Foxp3+ regulatory T lymphocytes (T-regs), and IFN-γ+ cytotoxic T lymphocytes (CTLs) in the different groups of tumor tissues to determine the effects of miR-200a on anti-tumor immunity in vivo." (PMID 31981455, 2020). "Immunohistochemistry for CD4, CD8, Foxp3, Granzyme B (GZMB), PDL1, and HLA class I was performed in tumor biopsies collected before and after DC vaccination." (PMID 31649669, 2019). "Tregs, a population characterized by FoxP3+ CD25+ CD4+ T cells, significantly suppress immune responses, and it has been shown that their depletion effectively eradicates tumor cells via an enhanced anti-tumor immune response." (PMID 31192215, 2019). "Tumor biopsies from primary lesion were analyzed for the expression and localization of CD8, FoxP3, PD-1, and PD-L1 by immunohistochemistry." (PMID 31138162, 2019). "In this study, the expression and localization of CD8, FoxP3, PD-1, and PD-L1 in NPC tumor tissues was evaluated by immunohistochemical staining." (PMID 31138162, 2019). "In a BRAF-mutated model of mouse melanoma, the BRAF-inhibitor PLX4720 selectively decreased the number of CD4+Foxp3+ Treg cells and of CD11b+Gr1+ myeloid-derived suppressor cells (MDSC) in the tumor microenvironment." (PMID 31762942, 2019). "To confirm these findings using an orthogonal approach, we used immunofluorescence to detect the tumor cell marker, cytokeratin, a pan T cell marker CD3, and the Treg marker, Foxp3." (PMID 31291990, 2019). "Patients were grouped into low- and high-frequency groups based on tumour-infiltrating lymphocytes (TILs) according to a median value of 252/4HPFs for CD3+ TILs, 96/4HPFs for CD8+ TILs, and 0/4HPFs for Foxp3+ TILs." (PMID 31882943, 2019). "Baseline tumor biopsies from patients with NSCLC (n = 1) and SCCHN (n = 4) were analyzed for the presence of PD-L1, CD8, FoxP3, and 4-1BB/CD137." (PMID 31801624, 2019). "Vaccination with irradiated cells overexpressing GM-CSF or IL-21 alone significantly inhibited tumor growth and led to significantly more CD4+ CD8+ T cells and fewer CD4+ Foxp3+ T cells in the spleen and xenograft." (PMID 31467912, 2019). "qRT-PCR results also showed that the expression of FOXP3 and CCL20 mRNA in tumor tissues is greater than in NATs and CCL20 and FOXP3 mRNA expression were significantly correlated." (PMID 31852159, 2019). "Because Foxp3 Tregs inhibit the activity of CD8+ T cells, these cells have been examined in many studies, and their relationship with the tumor microenvironment in HPV−induced SCC remains ambiguous." (PMID 31510065, 2019). "We and others have reported that the presence of tumor-infiltrating CD4+ or CD8+ T cells and the ratio of tumor-infiltrating FOXP3+ Tregs to CD4+ T cells were favorable and unfavorable prognosticators, respectively, in patients with PDAC." (PMID 30800224, 2019). "We also found that lactate enhances tryptophan metabolism and kynurenine production by pDCs which contribute to induction of FoxP3+ CD4+ regulatory T cells, the major immunosuppressive immune cell subset in tumor microenvironment." (PMID 31440253, 2019). "iTreg differentiation is driven by the master transcription factor, Foxp3, which is transcriptionally activated by TGFβ effectors, pSmad3 and Smad4, we thus postulated that suppression of Treg activation through blockade of TGFβ ligands might enhance α-PD-1 tumor responses." (PMID 30832732, 2019). "The number of infiltrated CD4+ helper T cells, FoxP3+ regulatory T cells, and CD45R+ B lymphocytes was also small in the tumor lesions of PKF and PKF2h mice." (PMID 30659170, 2019). "The main mode of action of L-NAME was its capacity to activate DC and to reduce Treg accumulation in tumor beds, thereby increasing the CD8+/FOXP3 ratio in the context of a long-term PD-1 blockade." (PMID 31481761, 2019).